TNF (tumor necrosis factor)
Diseases named in the same sentence as TNF in open-access papers (continued):
Sharing a sentence is not in itself a finding about the gene and the disease.
Insulin resistance (continued). "TNF is, in turn, responsible for insulin resistance in humans, and exercise may protect against TNF-induced insulin resistance in part due to its anti-inflammatory effects mediated by muscle-derived IL-6." (PMID 39199416, 2024). "In addition, hepatic insulin resistance is observed with increased TNF-α expression in AT when macrophages are recruited to AT by the overexpression of MCP1." (PMID 38750502, 2024). "Gefitinib may be of value in the treatment of type I diabetes mellitus by inhibition of TNF-α, leading to reduction in inflammation, decreased insulin resistance and slowed progression of Beta-cell destruction." (PMID 38362147, 2024). "A disorder in this tissue triggers reduced production of adipocytokines, such as adiponectin, and upregulation of the expression of leptin, tumor necrosis factor-α (TNF-α), and interleukin-6 (IL-6), promoting insulin resistance in association with increased visceral adiposity." (PMID 39273464, 2024). "Moreover, insulin resistance increases circulating pro-inflammatory cytokines, such as TNF-α and IL-6, through exacerbated oxidative stress." (PMID 39125385, 2024). "Moreover, TNF-α primarily contributes to insulin resistance and type 2 diabetes by blocking insulin-regulated glucose transporter 4 in adipocytes, skeletal muscles, and cardiac muscles." (PMID 39149648, 2024). "In the previous study, we confirmed TNF-α could induce hepatic insulin resistance both in vitro and in vivo." (PMID 38713402, 2024). "Additionally, in vivo studies showed that asprosin increased endoplasmic reticulum stress, glucose intolerance, insulin resistance, and the flow of pro-inflammatory cytokines (monocyte chemoattractant protein-1, IL-6, and TNF)." (PMID 38217801, 2024). "In a study on the contribution of TNFα to insulin resistance (IR), the authors compared the transcriptional profiles of rat H‐411E hepatocytes exposed to insulin with or without TNFα, in which Gadd45β expression was upregulated by insulin and then reversed by TNFα." (PMID 39653679, 2024). "TNF-α activates T lymphocytes and macrophages, inducing the production of other cytokines and cell adhesion molecules and potentially inducing insulin resistance by reducing insulin signaling and promoting the serine phosphorylation of insulin receptor substrate 1 (IRS1)." (PMID 39408723, 2024). "The glycogen was detected after stimulating cells with 100 nM insulin, the reduction of glycogen in TNF-α-induced HepG2 and the increase of glycogen in lrisin-treated cells were used to evaluate insulin resistance model and anti-insulin resistance activity of lrisin, respectively." (PMID 39749015, 2024). "Finally, the gut microbiota regulates the production of cytokines, such as tumor necrosis factor-alpha (TNF-alpha), which plays a key role in regulating inflammation and insulin resistance." (PMID 39211341, 2024). "To examine whether the inflammatory and insulin resistance state could be maintained beyond 24 h, we treated adipocytes with 12 h TNF-α and 24 h hypoxia and then provided the treated cells with glucose and FBS." (PMID 39415617, 2024). "Additionally, SPs from seaweeds mitigated inflammation and insulin resistance, as evidenced by reduced TNF-α levels and serum insulin concentrations, particularly in obese animal models." (PMID 39728103, 2024). "This research supports the role of TNF-α in insulin resistance." (PMID 39149648, 2024). "It is reported that TNF-α has been linked to signaling pathway of insulin impairment by increasing serine phosphorylation of IRS-1, which inhibits activity of tyrosine kinase resulting in impaired downstream signaling and development of insulin resistance." (PMID 37089941, 2023). "Treatment with 50 mg/kg CBD oil by oral gavage was able to reduce white adipose tissue and revert insulin resistance in males, reduce plasma triglycerides in females, and attenuate plasma LPS levels and overexpression of TNFα and IL6 in the hypothalamus of both sexes." (PMID 36969815, 2023).
Insulin resistance (continued). "Hesperidin could also affect insulin levels and insulin resistance by modulating inflammation since it has been shown that inflammatory markers, including leptin, IL-6, and TNF-α, play a role in the pathogenesis of DM and the development of insulin resistance." (PMID 37502716, 2023). "In this regard, it is reported that TNF-α could play a role in the development of insulin resistance in humans, both in muscle and in vascular tissue." (PMID 36983240, 2023). "Certain adipocytokines, such as interleukin-1, tumor necrosis factor-α (TNF-α), visfatin and leptin, and increased oxidative stress that occurs in some cases of hypothyroidism, may coincide with the development of insulin resistance." (PMID 37600722, 2023). "Taken together, these studies present the tantalizing but still unproven hypothesis that IL-6 and TNF-α in conjunction directly modulate insulin resistance, androgen excess, and ovulatory dysfunction in PCOS." (PMID 37195871, 2023). "Our data suggest that TNFα is a key regulator of hepatic inflammation and insulin resistance associated with the development of early non-obese MASH." (PMID 37683301, 2023). "We found that JAZF‐1 and PPAR‐γ could promote Tregs differentiation and regulate insulin resistance by synergistically decreasing the expression levels of TNF‐α, IL‐1β and IL‐6 and increasing those of IL‐10 and TGF‐β." (PMID 36734198, 2023). "Along with increased body weight and insulin-resistance conditions, serum proinflammatory cytokines, including IL-6 and TNF-α, also showed a significant increase in comparison with the ND group, which were reversed after treating mice with orlistat and both doses of O. aristatus for two months." (PMID 36678606, 2023). "The higher prevalence of T2DM in COPD patients, even in mild cases and independent of steroid use, may be attributed to elevated levels of inflammatory mediators such as TNF-a and IL-6, which can lead to insulin resistance." (PMID 37900064, 2023). "The abundances of fecal isobutyric acid negatively correlated with fasting plasma glucose, insulin, cholesterol, triglycerides, tumor necrosis factor-α, plasminogen activator inhibit-1, monocyte chemotactic protein-1 and homeostatic model assessment of insulin resistance (p < 0.01)." (PMID 38004641, 2023). "Insulin resistance can cause adipose tissue to secrete leptin, IL-6, TNF-α and other adipocytokines, and interact with these factors to cause the ‘second hit’, in which TNF-α plays a key role in this stage." (PMID 38041076, 2023). "But, excessive expression of TNF-α in adipose tissue may result in high blood glucose levels and insulin resistance." (PMID 37346347, 2023). "Hence, MMP3 seems to play a role in fatty-acid induced insulin resistance and angiogenesis through regulation of tumor necrosis factor α (TNFα) and the proangiogenic factor vascular endothelial growth factor (VEGF), respectively." (PMID 37445827, 2023). "This inflammatory state increases the secretion of proinflammatory cytokines (adipokines), such as tumour necrosis factor alpha (TNFα), interleukins 1 and 6 (IL-1 and IL-6) and leptin, which generates insulin resistance, the inhibition of protein synthesis and an increase in muscle catabolism." (PMID 36626317, 2023). "Specified oral taxa may contribute to shifting energy expenditure by aiding insulin resistance by raising tumor necrosis factor-alpha (TNF-α) and lipopolysaccharide levels." (PMID 36674680, 2023). "TNF-α overexpression plays a crucial role in the development of insulin resistance which is an important component of MetS, and some research suggested that TNF-α could be an early predictor for MetS detection." (PMID 36596839, 2023). "Furthermore, TNF-α can act as an inhibitor of peripheral insulin action by inducing serine phosphorylation of insulin receptor substrate-1 which leads to insulin resistance." (PMID 37215099, 2023).
Insulin resistance (continued). "Insulin resistance and hyperinsulinemia promote the production of pro-inflammatory cytokines such as tumor necrosis factor-alpha (TNF-α) and interleukin-6 (IL-6), leading to increased oxidative stress and impaired nitric oxide (NO) bioavailability, which in turn promotes endothelial dysfunction." (PMID 37367870, 2023). "Furthermore, TNF-alpha shows a positive correlation with glucose levels; it is known TNF-alpha has been shown to induce insulin resistance and impair glucose uptake in cells, leading to hyperglycemia." (PMID 37629267, 2023). "Besides, mitochondrial damage produces a large amount of ROS, which induces the release of inflammatory factors [such as TNF-α, interleukin 1β (IL-1β) and IL-6] and disrupts pancreatic β-cell function, further aggravating insulin resistance." (PMID 37828472, 2023). "In addition, HS-fed mice presented with adipose tissue and liver inflammation characterised by increased levels of TNFα, a cytokine involved in adipocyte hypertrophy, fat deposition, insulin resistance, and hyperglycaemia (for review see:)." (PMID 37631015, 2023). "TNF-α plays a significant role in this situation because of the buildup of fat in adipose tissue due to its production and release during inflammation, which promotes insulin resistance and increases lipolysis." (PMID 37241737, 2023). "It has been demonstrated that TNF-α interferes with the insulin receptor signaling pathway and with metabolism of glucose transporters, and, consequently, plays a role in the pathophysiology of insulin resistance." (PMID 38256882, 2023). "It was reported that increased synthesis of cellular GM3 might be involved in tumor necrosis factor-α (TNF-α)-induced insulin resistance in cultured adipocytes." (PMID 36827398, 2023). "Notably, in this model, hyperhomocysteinemia leads to elevations in TNF-α, IL-6, and MCP-1 and exaggerates insulin resistance, risk factors for cardiovascular diseases observed in PCOS." (PMID 37195871, 2023). "Tumor necrosis factor alpha (TNF-α, also known as TNF superfamily member 2 (TNFSF2) or simply TNF) is a pluripotent cytokine that may be involved in metabolic disorders such as insulin resistance and is associated with type 2 diabetes." (PMID 37446334, 2023). "Thereby improving insulin resistance, and TNF can trigger the activation of the MAPK pathway." (PMID 37000070, 2023). "Therefore, the regulation of both TNF-α and adiponectin and the regulation of proteins, involved in the insulin pathway, lead to the protection against insulin resistance." (PMID 36647430, 2023). "Brain insulin resistance occurs through the release of pro-inflammatory cytokines; peripherally produced pro-inflammatory cytokines such as TNF-α, IL-6, IL-12 and IL-1β can cross the blood-brain barrier, leading to neuroinflammation and central insulin resistance." (PMID 37415663, 2023). "In addition, IL-1β increases the expression of PGE2, and TNF-α leads to insulin resistance and the accumulation of AGEs, exacerbating diabetes." (PMID 37374121, 2023). "Based on our findings, there appears to be a noteworthy and affirmative correlation between serum levels of CCN5 and the risk of developing GDM, as well as its associated risk factors such as BMI, insulin resistance index, FBG, and inflammatory cytokines TNF-α and IL-6." (PMID 37794318, 2023). "TNF-α, which plays an important role in regulating skin dryness, acts on insulin receptors present on the inner walls of blood vessels and inhibits their activity, resulting in a state of insulin resistance." (PMID 37374121, 2023). "The role of TNF-α in this inflammatory scenario is also related to insulin resistance." (PMID 38813486, 2023). "Similarly, 22R-hydroxycholesterol is a natural ligand for the liver X receptor [LXR], and activation of LXR improves TNFα-induced insulin resistance in brown adipocytes." (PMID 36890514, 2023).
Insulin resistance (continued). "TNFα is a proinflammatory cytokine produced and upregulated in adipose tissue macrophages in conditions of obesity and Type 2 diabetes (T2D), where it promotes lipolysis and induces insulin resistance." (PMID 37237488, 2023). "Adipocytes and resident macrophages that have migrated to the adipose tissue produce and secrete adipocytokines, including tumor necrosis factor-α, interleukin-6, resistin, and adiponectin, which are thought to contribute to the development of insulin resistance and T2D." (PMID 37680885, 2023). "•TNFα is a key regulator of hepatic inflammation and insulin resistance." (PMID 37683301, 2023). "TNF-α, IL-1β, and IL-6 released by adipose tissue resident macrophages could lead to insulin resistance." (PMID 37693353, 2023). "TNF-α overexpression plays a crucial role in the development of insulin resistance, which is an important component of MetS, and the available systematic review suggested that TNF-α could be an early biomarker for MetS detection." (PMID 36596839, 2023). "It decreases fat mass related to reduced insulin resistance, tumor necrosis factor α (TNFα), interleukin-6 (IL-6), as well as decreased activity of the c-Jun N-terminal Kinase (JNK) and IκB kinase subunit β (IKKβ); thus, in liver and muscle, glutamine improves insulin signaling." (PMID 37696865, 2023). "This suggests that CCN5 may play a role in the development of GDM, as there was a direct and significant correlation between CCN5 and several risk factors for GDM, including BMI, insulin resistance index, FBG, and inflammatory cytokines (IL-6 and TNF-α)." (PMID 37794318, 2023). "Because adipose tissue with an excessive amount of FFA, resistin, TNF-α, interleukin-6, and other substances might result in insulin resistance." (PMID 37763170, 2023). "As a result, levels of TNF, a recognized modulator of insulin resistance, rise even more." (PMID 36835217, 2023). "Similarly, silybin treatment reduced the expression levels of TNF-α and NF-κB in high-fat mice, reducing body weight and insulin resistance." (PMID 38239743, 2023). "Insulin resistance in metabolic syndrome may result from the high secretion of TNF-α and the low secretion of IL-10." (PMID 38202328, 2023). "Screening identifies TNFα and IL1β as the mediators of insulin resistance in iPSC-Heps." (PMID 37400454, 2023). "Thus, resistin both induces insulin resistance and impairs insulin secretion in pancreatic beta cells, as well as tumor necrosis factor α (TNF-α) and fetuin-A." (PMID 37373556, 2023). "Our research indicates a noteworthy and affirmative correlation between the levels of CCN5 in the serum and the risk of developing GDM, along with its associated risk factors such as BMI, insulin resistance index, FBG, and inflammatory cytokines (TNF-α and IL-6)." (PMID 37794318, 2023). "The TNF signaling pathway's essential protein is TNF-α, which is one of the major proinflammatory mediators and induces low-leveltissue-specific inflammation by activating IKKβ and promoting the development of insulin resistance and the onset of T2DM." (PMID 36818229, 2023). "T2DM is a multi-factorial non-communicable disorder that is notorious for causing insulin resistance and long-lasting sub-clinical inflammation with elevated systemic levels of adipokines, tumor necrosis factor (TNF) and interleukins (IL)." (PMID 37238986, 2023). "In addition, hesperidin improves insulin resistance, hypertension, hyperglycemia, hypercholesterolemia, triglyceride, TNF-α, and hs-CPR levels in the blood." (PMID 36768946, 2023). "Maternal TNFα levels in pregnancy are independently associated with higher maternal insulin resistance and in non-pregnant individuals TNFα overexpression is characteristic of T2D." (PMID 38288471, 2023). "Moreover, TNFα was identified as a mechanistic link between inflammation and metabolism by inducing insulin resistance and metabolic effects on immune cells." (PMID 37553427, 2023).
Insulin resistance (continued). "It has been suggested that TNF-α might be involved in insulin resistance development via different mechanisms, such as suppression of insulin receptor signaling." (PMID 37512149, 2023). "Both peptides could also enhance insulin signaling and mitigated insulin resistance in TNF-α-stressed preadipocytes." (PMID 37111032, 2023). "In addition, brown adipose tissue releases pro-inflammatory mediators such as IL-8, IL-4, IL-1, IL-6, TNF-α, and histamine in response to high blood glucose levels and improved insulin resistance." (PMID 37241737, 2023). "Moreover, these cytokines and inflammatory mediators, particularly TNF-α, monocyte chemotactic protein-1 (MCP-1), CRP, and interleukins, are considered as the potential cause of insulin resistance or impaired B cell function." (PMID 36769405, 2023). "Furthermore, a relationship between TNFα secretion and hepatic insulin resistance has been reported, thus linking inflammation and metabolism as possible driver for the MAFLD-related extrahepatic conditions." (PMID 37620891, 2023). "Moreover, high TNF levels have been associated with alterations in insulin signaling, and treatment with neutralizing TNF antibodies has improved insulin resistance." (PMID 37374323, 2023). "The expression of TNF-α is increased in human adipose tissues with insulin resistance." (PMID 37215099, 2023). "Although the directionality of the association between MAFLD and psoriasis has not been clearly determined, the excess production of pro-inflammatory cytokines produced by lymphocytes and keratinocytes present in psoriatic skin (e.g., IL-6, TNF-α, IL-17) are believed to mediate insulin resistance." (PMID 36836776, 2023). "For example, the redistribution of fat could lead to increased secretion of tumor necrosis factor-α (TNF-α), resulting in insulin resistance secondary to inflammation." (PMID 36768699, 2023). "Moreover, the elevation in circulating IL-6, TNF-a, and CRP levels caused by periodontitis contributes to increased systemic inflammation, thus further aggravating insulin resistance in patients with T2DM." (PMID 38098816, 2023). "NAFLD is the hepatic manifestation of multiple organ cross-talk due to shared mechanisms, including insulin resistance and chronic inflammation factors such as tumor necrosis factor-alpha and interleukin-6, which contribute to increased CVD events and risk of cardiovascular mortality." (PMID 36837575, 2023). "Treatment with C. odorata and coumarin offered an anti-hypertensive effect and caused modulation in insulin resistance, possibly through its effect on amended oxidative stress biomarkers (SOD, CAT, and MDA), inflammatory mediators (TNF-α and IL-6) and improved insulin sensitivity." (PMID 37033655, 2023). "The reduced level of miR-124 could promote progression to T2DM through interactions with NF-κB, TRAF-6, and cytokines (TNFα and IL-6), which lead to insulin resistance, poor glycemic control, and a pro-inflammatory state." (PMID 37628595, 2023). "TNF can inhibit insulin-induced tyrosine phosphorylation of insulin receptor substrate 1 (IRS1) and glucose uptake, and promote degradation of the GKAP42 protein in adipocytes, thus causing T2DM and insulin resistance." (PMID 36747287, 2023). "Research now shows that TNF-α and IL-6 are fat factors which induce insulin resistance." (PMID 36997952, 2023). "Distinctly, TNFα is able to induce insulin resistance by reducing the messenger RNA expression for glucose transporter 4 (GLUT4), a trans-membrane channel for glucose uptake into peripheral tissues, and to mobilize lipids from adipocytes, decreasing lipoprotein lipase activity." (PMID 38137918, 2023). "Studies have shown that HP infection induces the release of pro-inflammatory cytokines such as tumor necrosis factor alpha, interferon gamma, interleukin (IL)-1, IL-6, IL-8, IL-10, IL-12, and C reactive protein and was shown to be involved in the pathogenesis of insulin resistance." (PMID 36699110, 2023).